TMUB2 (transmembrane and ubiquitin like domain containing 2)
Synonyms: FP2653; MGC3123
Tractability: Antibody: UniProt predicts a signal peptide or a membrane-spanning region. PROTAC: ubiquitination databases record sites on it.
Gene: Protein-coding gene on chromosome 17 (44,186,966 to 44,191,931, forward strand). Ensembl gene ENSG00000168591.
Subcellular location: Membrane
Subcellular location (Human Protein Atlas): Cytosol; Vesicles
Gene Ontology:
Molecular function: protein binding
Biological process: ERAD pathway
Cellular component: membrane
Genetic constraint (gnomAD): Loss-of-function variants: 17 observed, 20.11 expected, observed/expected ratio (o/e) 0.85, 90% interval 0.58 to 1.27. The upper end of that interval is the gene's LOEUF score, 1.27, which puts it in group 5 of 6, group 1 being the genes least tolerant of losing a copy. Missense variants: 410 observed, 414.65 expected, observed/expected ratio (o/e) 0.99, 90% interval 0.91 to 1.07. Synonymous variants: 183 observed, 172.61 expected, observed/expected ratio (o/e) 1.06, 90% interval 0.94 to 1.2.
Homologues: Orthologues: macaque TMUB2 (98% identical), chimpanzee TMUB2 (97% identical), dog TMUB2 (95% identical), pig TMUB2 (91% identical), rabbit TMUB2 (88% identical), mouse Tmub2 (86% identical), rat Tmub2 (83% identical), guinea pig TMUB2 (76% identical), tropical clawed frog tmub2 (49% identical), zebrafish tmub2 (44% identical), Caenorhabditis elegans B0303.4 (26% identical). Paralogues in human: TMUB1 (31% identical).